A4GNT (alpha-1,4-N-acetylglucosaminyltransferase)
Description:
Catalyzes the transfer of N-acetylglucosamine (GlcNAc) residues from UDP-N-acetyl-alpha-D-glucosamine donnors to beta (1->4)- linked or beta-(1->3)-linked galactose residues on O-glycans like core 2 branched O-glycans. Necessary for the synthesis of type III mucin which is specifically produced in the stomach, duodenum, and pancreatic duct. May protect against inflammation-associated gastric adenocarcinomas (By similarity).
Synonyms: Alpha4GnT
Tractability: Antibody: UniProt predicts a signal peptide or a membrane-spanning region.
Gene: Protein-coding gene on chromosome 3 (138,122,901 to 138,132,390, reverse strand). Ensembl gene ENSG00000118017.
Subcellular location: Golgi apparatus membrane
Pathways (Reactome):
Metabolism of proteins: O-linked glycosylation of mucins
Gene Ontology:
Molecular function: acetylglucosaminyltransferase activity; hexosyltransferase activity
Biological process: glycoprotein biosynthetic process; carbohydrate metabolic process; protein O-linked glycosylation; protein O-linked glycosylation via N-acetyl-galactosamine
Cellular component: Golgi membrane; membrane
Genetic constraint (gnomAD): Loss-of-function variants: 6 observed, 8.56 expected, observed/expected ratio (o/e) 0.7, 90% interval 0.38 to 1.38. That is too few expected variants to judge how well the gene tolerates losing a copy. Missense variants: 376 observed, 436.9 expected, observed/expected ratio (o/e) 0.86, 90% interval 0.79 to 0.94. Synonymous variants: 156 observed, 167.98 expected, observed/expected ratio (o/e) 0.93, 90% interval 0.81 to 1.06.
Homologues: Orthologues: chimpanzee A4GNT (99% identical), pig A4GNT (80% identical), rabbit A4GNT (80% identical), dog A4GNT (80% identical), guinea pig A4GNT (76% identical), rat A4gnt (74% identical), mouse A4gnt (71% identical), tropical clawed frog a4galtl (50% identical), tropical clawed frog a4gnt (45% identical), Drosophila melanogaster alpha4GT1 (23% identical), Drosophila melanogaster alpha4GT2 (23% identical), Caenorhabditis elegans C01G5.7 (9% identical). Paralogues in human: A4GALT (34% identical).
Diseases named in the same sentence as A4GNT in open-access papers:
A4GNT is named in the same sentence as 11 diseases in open-access papers, as found by Europe PMC text mining. Sharing a sentence is not in itself a finding about the gene and the disease. The quoted sentences say what the papers report.
gastric cancer (7 papers, 2012 to 2025). A primary or metastatic malignant neoplasm involving the stomach. "A4gnt KO mice deficient in the gene encoding for α1, 4-N-acetylglucosaminyltransferase notably develop gastric cancer in a spontaneous manner of hyperplasia-dysplasia-adenocarcinoma sequence." (PMID 31873082, 2019). "The altered gastric microbiome may thus partially account for the development of gastric cancer in the context of deficiency of A4GNT." (PMID 40012782, 2025). "Meanwhile, 34 isolated from the brown algae Eisenia bicyclis restrained the progressive development of a precancerous lesion, gastric dysplasia, in alpha-1,4-N-acetylglucosaminyltransferase (A4gnt) KO mice, a unique animal model for gastric cancer." (PMID 38535455, 2024). "This was evaluated in A4gnt KO mice that spontaneously developed gastric adenocarcinoma, a type of cancer that is consistent with differentiated-type gastric cancer." (PMID 36673507, 2023). "At 10–20 weeks of age, the age used in the present study, A4gnt KO mice show precancerous lesion of gastric cancer, dysplasia." (PMID 34210998, 2021). "Deletion of A4gnt has been shown to induce a complete loss of α-GlcNAc expression and spontaneous development of gastric cancer, even in the absence of H. pylori infection in mice." (PMID 40012782, 2025). "Furthermore, the knockdown of A4GNT significantly influences gastric development, gradually leading to gastric dysplasia, precancerous lesion of gastric cancer, dysplasia." (PMID 37808112, 2023). "A4gnt KO mice are a mutant mouse model that spontaneously develops gastric cancer through hyperplasia-dysplasia-adenocarcinoma sequence in the antrum of the stomach, and we observed the effects of E. gracilis and paramylon on the early involvements of A4gnt KO mice." (PMID 34210998, 2021). "However, as A4gnt KO mice develop only precancerous lesion, gastric dysplasia, at the age we used in the present study, and we did not investigate the effects of Euglena and paramylon on gastric cancer in this study, it is impossible to discuss about cancer-preventing effects of these compounds." (PMID 34210998, 2021).
gastric adenocarcinoma (5 papers, 2019 to 2025). "Furthermore, a separate study utilized knockout mice deficient in alpha-1,4-N-acetylglucosaminyltransferase (A4gnt) to explore the development of gastric dysplasia and its progression to gastric adenocarcinoma." (PMID 40673273, 2025).
lymph node metastasis (1 paper, 2019). "However, both α4GnT- and αGlcNAc-positive cases consistently showed a lower frequency of lymph node metastasis and pelvic dissemination relative to negative cases (P = 0.175 for α4GnT, and P = 0.159 for αGlcNAc)." (PMID 31506488, 2019). "In GAS patients, we did not observe significant differences in clinicopathological findings, such as patient age, FIGO stage, lymph node metastasis and ascites cytology, between cases positive or negative for MUC6, αGlcNAc and α4GnT markers." (PMID 31506488, 2019).
uterine cervix tumor (1 paper, 2019). "Further studies will be of great significance to address molecular mechanisms underlying regulation of gastric type cervical tumor progression by α4GnT." (PMID 31506488, 2019). "In conclusion, our work indicates that αGlcNAc catalyzed by α4GnT is relevant to two important developments in uterine cervix tumor, gastric type: one a positive correlation with the transition to LEGH from NNEG." (PMID 31506488, 2019).
adenocarcinoma (4 papers, 2019 to 2025). A common cancer characterized by the presence of malignant glandular cells. "The sequence of histopathological changes, including hyperplasia, low-grade dysplasia, high-grade dysplasia, and adenocarcinoma, paralleled that observed in single A4gnt knockout mice, though adenocarcinoma occurred with slightly lower incidence." (PMID 40673273, 2025). "Subsequently, high-grade dysplasia appeared by 20 weeks, and by 50 weeks, adenocarcinoma was present in all A4gnt knockout (A4gnt−/−) mice." (PMID 40673273, 2025). "A key step for this mechanism is the synthesis of the evolutionary conserved, unusual peripheral glycan αGlcNAc by α1,4-N-acetylglucosaminyltransferase (α4GnT); mice lacking this enzyme spontaneously develop adenocarcinoma in the gastric antrum." (PMID 31801293, 2019).
cancer (4 papers, 2013 to 2023). A tumor composed of atypical neoplastic, often pleomorphic cells that invade other tissues. "Here, we extend these observations to predict malignant potential of an advanced cancer, in that αGlcNAc and α4GnT expression was significantly correlated with benign prognosis of GAS patients." (PMID 31506488, 2019).
tumor (2 papers, 2012 to 2019). "Furthermore, decreased expression of α4GnT and αGlcNAc in follow-up biopsy of LEGH patients’ uterine cervix was closely associated with tumor progression to unfavorable GAS." (PMID 31506488, 2019). "Our immunohistochemical analysis of α4GnT and αGlcNAc expression in cervical resected specimens provides important tools for diagnosis of uterine cervical tumor, gastric type, and promotes understanding of tumor development." (PMID 31506488, 2019). "However, molecular function of α4GnT in tumor progression remains to be clarified." (PMID 31506488, 2019).
infection (1 paper, 2018). The state of being infected such as from the introduction of a foreign agent such as serum, vaccine, antigenic substance or organism. "Soon after infection of the bovine GI tract, both C. oncophora and O. ostertagi induced expression of the mucin glycan biosynthesis enzyme gene Gcnt3, in addition to Gcnt4 and A4gnt induced by O. ostertagi, further supporting that changes in the mucus niche occur during infection." (PMID 29912166, 2018).
A4GNT also shares sentences with these, for which no sentence is quoted: dysplasia (2 papers); hyperplasia (1); Obesity (1).